INS (insulin)
Diseases named in the same sentence as INS in open-access papers (continued):
Sharing a sentence is not in itself a finding about the gene and the disease.
diabetes (continued). "Insulin was discovered in 1921, following years of research to find a treatment for diabetes." (PMID 38276493, 2023). "A dysfunctional adipocyte can play a key role in the development of diabetes, as defects in insulin action in adipocytes may lead to systemic insulin resistance with impaired insulin action in muscle and liver." (PMID 37242297, 2023). "It is a non-autoimmune form of insulin-dependent diabetes mellitus resulting from selective pancreatic β-cells loss and impaired insulin secretion." (PMID 36982670, 2023). "Also, in persons with diabetes who are at the beginning of the disease and don’t need insulin injection, endogenous insulin increases as a compensatory mechanism." (PMID 37828117, 2023). "This capacity of PVP/AlgPBA microspheres could be used both in the development of glucose sensors and in the treatment of diabetes by encapsulation of insulin (theranostic applications)." (PMID 36771883, 2023). "Diabetes mellitus (DM) is a chronic metabolic disorder characterized by hyperglycemia and disturbances of carbohydrate, fat, and protein metabolism resulting from defects in insulin secretion, insulin action, or both." (PMID 37512570, 2023). "Furthermore, the leptin level has been reported to be lower before the start of insulin treatment in patients newly diagnosed with diabetes than in healthy controls." (PMID 37670877, 2023). "It is possible to have an improvement in insulin resistance and natriuresis by inhibiting the reabsorption of sodium and glucose at the proximal tubules in the kidney, and a decrease in cardiovascular mortality in patients with diabetes mellitus (DM)." (PMID 36909046, 2023). "It has recently been reported that the prefrontal cortex plays a dominant role in controlling food selection and intake, and its function may change in patients with diabetes due to its dependence on insulin metabolism." (PMID 37091855, 2023). "Another interesting observation emerging from our study was that all the SARS-CoV-2 autoantibody positive T1D patients with diabetes immunoreactivity were positive for insulin autoantibodies, significantly more frequently than T1D patients negative for nucleocapsid SARS-CoV-2 Abs." (PMID 37171699, 2023). "This solution can target senescent adipocyte progenitor cells, reducing adipose tissue inflammation, increasing adipose tissue and peripheral insulin sensitivity, as well as promoting adipocyte progenitor cell development, ultimately treating diabetes in the elderly." (PMID 38273819, 2023). "It has been reported that obesity and diabetes can promote a variety of metabolic alterations, including abnormal lipid and carbohydrate metabolism, insulin resistance, altered activities of adipocyte hormones, disturbance in micronutrient metabolism, and elevated oxidative stress." (PMID 36344649, 2023). "Diabetes mellitus (DM) is a chronic hyperglycemic condition caused by a group of metabolic disorders marked by a lack of insulin production, insulin activity, or both." (PMID 36769571, 2023). "High free fatty acids may impair insulin sensitivity, creating a vicious cycle between high TG levels and IR, which may lead to impaired glucose tolerance and the development of diabetes." (PMID 37576966, 2023). "Furthermore, we think that by addressing the causes of the most difficult point, we can improve adherence with insulin use, which will help control diabetes." (PMID 37474582, 2023). "Overall, the basic mechanisms of hawthorn extract against diabetes may be related to inhibiting intestinal α-glycosidase, reducing hepatic gluconeogenesis, improving lipid metabolism, and restoring insulin sensitivity." (PMID 37151681, 2023). "Practical implications emphasize the need for tailored interventions focusing on enhancing user trust, ensuring ease of use, and addressing concerns related to privacy risks to facilitate wider acceptance and uptake of wearable insulin biosensors in diabetes management." (PMID 38239544, 2023).
diabetes (continued). "The development of diabetes under these conditions may be due to the influence of adipokines (leptin and resistin), as they stimulate or reduce the secretion of insulin (a hormone that controls serum glucose levels)." (PMID 36875280, 2023). "In this study, we found that patients with diabetes were more likely to choose premixed insulin." (PMID 37250086, 2023). "Additionally, more supportive policies should be implemented for the uninsured diabetes population to get enough necessary insulin usage." (PMID 36751859, 2023). "A CRISPR knock-out screen in mouse pancreatic beta cells identified seven NuA4/TIP60 subunits (Tip60, ING3, DMAP1, p400, BRD8, BAF53A and MRGBP) as positive regulators of insulin secretion, involving the complex in beta cell function and arguing for a potential role in diabetes." (PMID 37091973, 2023). "The indications for insulin pump treatment were mainly hypoglycaemia and instable diabetes." (PMID 37185052, 2023). "Diabetes, associated with elevated fasting blood sugar (FBS) and insulin levels, disrupts the normal biological functioning, and significantly increases the risk of conditions such as retinopathy, coronary heart disease, renal failure, neuropathy, and various types of cancer." (PMID 37762686, 2023). "The production of ROS and the resulting oxidative stress state play a crucial role in the pathogenesis of diabetes, which is closely related to impaired glucose utilization, insufficient insulin secretion, and insulin resistance and ultimately leads to chronic hyperglycemia." (PMID 37664859, 2023). "Patients in the STAMPEDE trial, on the other hand, had more advanced T2D, with an average disease duration of more than eight years and a mean baseline glycated hemoglobin level of 8.9% to 9.5%, while being treated with about three diabetes medications, including insulin." (PMID 36819346, 2023). "Medication or insulin therapy may be necessary depending on the type of diabetes and its progression." (PMID 37927470, 2023). "An impaired insulin signaling could then manifest as type 2 diabetes mellitus (T2DM) at the peripheral level and as AD at the central level." (PMID 37445790, 2023). "Diabetes mellitus is among the most common non-communicable metabolic diseases that is caused by a deficiency in or diminished effectiveness of endogenous insulin." (PMID 38139040, 2023). "However, individuals with diabetes experience difficulties in insulin secretion or sensitivity, leading to persistently elevated blood glucose levels." (PMID 37998166, 2023). "Results revealed that non-canonical Wnt5a signaling and JNK activity correlated with vascular reluctance to insulin action and to induce endothelial dysfunction, thus offering a novel therapeutic opportunity to protect the vasculature in patients with diabetes mellitus." (PMID 36984870, 2023). "IR is a pathological condition in which insulin-mediated glucose uptake is impaired in insulin-sensitive tissue and plays a pivotal role in the pathogenesis of obesity-related metabolic diseases, such as type 2 diabetes mellitus, fatty liver disease, and cardiovascular disease." (PMID 36982812, 2023). "The primary outcome was the incidence of newly diagnosed gliomas according to waist circumference (WC), and subgroup analyses were performed according to demographic characteristics and diabetes status including disease duration, number of oral hypoglycemic agents, and insulin use." (PMID 36928679, 2023). "Hepatic insulin clearance (HIC) is an important pathophysiology of type 2 diabetes mellitus (T2DM)." (PMID 38115089, 2023). "Indeed, EVs can transport pancreatic inslet antigen 2 (IA2), anti-glutamate acid decarboxylase (GAD65), proinsulin and insulin in type 1 diabetes mellitus and citrullinated proteins in rheumatoid arthritis." (PMID 36763158, 2023).
diabetes (continued). "The algorithm working according to FL adjusts the insulin dose based on the measured blood glucose levels and the direction and speed of change in glycaemic values, imitating the logic followed by doctors treating diabetes." (PMID 37685946, 2023). "The RCRI identifies the following as predictors of adverse outcomes: past medical history (Ischemic heart disease, congestive heart failure, cerebrovascular disease, and diabetes mellitus on insulin), one laboratory finding (creatinine > 180 umol.l–1), and one surgical factor (high-risk surgery)." (PMID 37035307, 2023). "Dietary methionine restriction targets fibroblast growth factor 21 (FGF-21), protein phosphatase 2A (PP2A), and autophagy, which further improves insulin resistance, insulin sensitivity, and reduces diabetes-related complications partially due to reduction in ROS production." (PMID 36714968, 2023). "Diabetes mellitus (DM), referred to as diabetes, is a chronic, progressive metabolic disorder that occurs when blood glucose levels increase because the body cannot produce sufficient amounts of the hormone insulin or cannot use the insulin effectively." (PMID 37237607, 2023). "Interestingly, GLP-1 analogs, initially developed to manage diabetes, have piqued the interest of researchers due to their potential to enhance insulin sensitivity within the central nervous system (CNS)." (PMID 38002034, 2023). "Shorter diabetes duration also predicted a successful switch from insulin to liraglutide." (PMID 37589043, 2023). "However, in subjects with diabetes (fasting glucose > 7.0 mmol/L), fasting insulin progressively decreased with higher glucose levels, whereas IGF-I bioactivity was significantly lower than in subjects with NFG and IFG." (PMID 36901984, 2023). "Model 3 is adjusted for age, gender, baseline HbA1c or glucose, 2‐year HbA1c or glucose, fenofibrate or placebo allocation, systolic blood pressure, diabetes duration, prior cardiovascular disease, prior microvascular complications, baseline use of oral hypoglycemics, insulin, and antihypertensives." (PMID 37070713, 2023). "Diabetes mellitus is a set of diseases in which there is an increase and imbalance in blood glucose levels, which may be due to either impaired insulin production or systemic resistance to the effects of insulin." (PMID 38143687, 2023). "The lower rate of diabetes control in patients with a longer duration of diabetes may be due to a decrease in insulin secretion over time as the patient's own islet cells fail with the progression of diabetes." (PMID 37046317, 2023). "In addition to changes in growth factors, such as IGF-1 and TGFβ, insulin decreasing occurs in diabetics’ wound tissue." (PMID 36839917, 2023). "Therefore, to effectively control diabetes, there is an urgent need to find a painless and convenient method of insulin administration." (PMID 37376294, 2023). "Type 1 diabetes is an autoimmune disease in which beta cells in the pancreas are unable to produce the hormone insulin while in type 2 diabetes, the most common form of diabetes, the body is either resistant to insulin or incapable of producing sufficient amounts of insulin." (PMID 36982458, 2023). "In this article, we discussed a case of a 73-year-old male with a history of uncontrolled type 2 diabetes mellitus on long-term insulin and liraglutide who presented with abdominal pain, subjective fevers, dry heaves, tachycardia, and mildly reduced oxygen saturation." (PMID 37252522, 2023). "Diabetes management is conventionally delivered through modifications of diet and lifestyle and pharmacological treatment, using antidiabetic drugs, and ultimately insulin injections." (PMID 37032781, 2023). "Interestingly, we found that poor diabetes knowledge, such as poor knowledge of a patient’s insulin type or dosage or latest HbA1c level, and also poor medical follow-up are risk factors for hypoglycemia unawareness." (PMID 37964960, 2023).
diabetes (continued). "However, both HOMA-B and IGI, indices of insulin secretory function, were lower in the group with incident diabetes." (PMID 37109236, 2023). "Some of the parameter values that guarantee the consistency of simulated glucose-insulin dynamics with clinical observations were adopted, as we aim to establish phenomenological models describing the diabetes progression, instead of providing precise estimates of all the parameters." (PMID 36848379, 2023). "The American Diabetes Association recommends offering CGM to pediatric and adult patients with diabetes on multiple daily injections or continuous subcutaneous insulin infusion or “insulin pumps” who can use devices safely either by themselves or with a caregiver." (PMID 38993859, 2023). "These adipocyte-derived active molecules may compromise normal insulin signaling, resulting in insulin resistance and diabetes." (PMID 37047011, 2023). "The fundamental problems of diabetes are insulin resistance and impaired insulin secretion." (PMID 38094528, 2023). "We note that associations with lower insulin secretion when not corrected for insulin sensitivity are consistent with a protective effect, because, in people without diabetes, a higher insulin sensitivity results in a reduced need for insulin secretion." (PMID 37280435, 2023). "Less active life style and decreasing ASM may lead to decreasing insulin sensitivity and diabetes, which could also explain our results." (PMID 36937340, 2023). "IR inactivation using inhibitors or caloric restriction to lower blood glucose levels can be used clinically to reduce circulating insulin levels; however, these strategies are practically infeasible for patients with severe diabetes who need exogenous insulin administration." (PMID 37779149, 2023). "Furthermore, the use of anti-diabetes medications that increase insulin exposure often promote hypoglycemia (particularly during times of weight reduction), requiring increased caloric consumption to treat low blood sugars." (PMID 37990681, 2023). "Therefore, the severity of DM was evaluated in terms of the number of OHAs ≥3, duration of diabetes ≥5 years, or insulin use." (PMID 36707543, 2023). "Another experimental indication is pumping glucagon parenterally and insulin to treat diabetes." (PMID 37629010, 2023). "Diabetes is a metabolic, progressive, and chronic disease affecting millions of people all over the globe, classically featuring hyperglycemia consequent to changes in insulin secretion and/or insulin activity." (PMID 38098900, 2023). "Some studies report that depressive symptoms and diabetes-specific distress are associated with negative appraisals of insulin." (PMID 37237318, 2023). "Longitudinal studies, such as the UK Prospective Diabetes Study (UKPDS) and the Diabetes Control and Complications Trial (DCCT), have provided evidence that medications such as insulin and metformin, which enhance glucose control, are linked to a reduction in chronic complications." (PMID 38247481, 2023). "While HFD feeding does not cause beta cell failure or overt diabetes, beta cells need to undergo expansion and hypersecrete insulin to maintain near-normal glucose levels in this model." (PMID 36470401, 2023). "It is known that glycemic control, duration of diabetes, complications, and insulin use may influence costs and healthcare use." (PMID 37029362, 2023). "A well-known insulin secretagogue, glibenclamide, is effective in diabetes-induced mice." (PMID 37842332, 2023). "Disruption of this mechanism results in impaired insulin secretion and ultimately diabetes." (PMID 38007492, 2023). "Advanced diabetes technologies, including continuous glucose monitoring and sensor-augmented insulin pumps with low-glucose suspension systems, can reduce the frequency of hypoglycemia and the occurrence of severe hypoglycemia without aggravating glycemic control." (PMID 36769430, 2023). "Most have had diabetes for more than 5 years and were on insulin treatment." (PMID 36721139, 2023).
diabetes (continued). "The Diabetes Control and Complications Trial and its follow-up Epidemiology of Diabetes Interventions and Complications study reported that intensified insulin therapy, along with support and education, results in better long-term glucose control and delays the complications of T1DM." (PMID 36994279, 2023). "Reviewed evidence indicates that regular intake of curcumin can improve glucose and lipid metabolism, attenuate inflammation, strengthen intracellular antioxidant response, enhance insulin signaling, and amend gut permeability in preclinical models of diabetes and CVD." (PMID 36839303, 2023). "In addition, a change in autophagic activity plays a critical role in the development of immune response, insulin sensitivity, diabetes and other metabolic diseases, which promotes HCC development." (PMID 37361533, 2023). "Extended insulin boluses to cover glycemic peaks administered by advanced technology might help people with diabetes obtain better postprandial glycemic control when eating meals with high glycemic indices or cooked in styles that promote glycemic peaks." (PMID 37049494, 2023). "Most studies found lower liver weight and unchanged or lower organ index, with higher liver organ index values found in insulin-treated STZ-induced diabetes rats, suggesting that the higher liver organ indices in diabetic rats resulted from better insulin action by treatment of CHL, CCL, and CLL." (PMID 37692463, 2023). "In 2003, Fronczak and colleagues reported that maternal vitamin D intake during pregnancy had a protective effect on the child’s risk of developing IA by evaluating measures of GAD65, IA-2, and insulin autoantibodies in children from the Diabetes Auto Immunity Study in the Young (DAISY) study." (PMID 37892409, 2023). "In this review, we present recent findings concerning miRNAs in islets and in insulin-secreting cells, and their differential expression in diabetes, with a specific focus on miRNAs involved in β-cell apoptosis/proliferation and glucose-stimulated insulin secretion." (PMID 36869830, 2023). "Moreover, the RISE Study showed that insulin and metformin are ineffective in preventing β-cell decline in youth with both prediabetes and recently diagnosed Type 2 diabetes mellitus." (PMID 40303241, 2023). "Also, in the Diabetes Prevention Program, metformin was considered to improve insulin secretion relative to sensitivity." (PMID 37623862, 2023). "In current reviews based on animal model studies, nigella seed extracts were shown to support the treatment of diabetes by significantly decreasing fasting blood glucose levels and glucose levels 2 h after meals, thereby decreasing glycated hemoglobin and improving insulin tolerance." (PMID 37185722, 2023). "Insulin users may also have a protracted period of poor glycemic control before they start insulin treatment, as have been shown in a Pacific regional survey of patients with diabetes." (PMID 37196125, 2023). "For example, despite the severity of diabetes and its possible life-threatening complications in case resulting from inadequate treatment, only 32.4%, 35.3%, and 11.8% have in stock biguanides, sulfonylureas, and insulin respectively, out of the 34 visited." (PMID 36973655, 2023). "While insulin levels are low in diabetes, glucagon is present in excess." (PMID 37850072, 2023). "The mapping of this metagenome to GWASs identified loci of diabetes, and the enrichment of known molecular pathways of diabetes suggest a primary role of this metagenome in the pathogenesis of diabetes rather than merely a pathophysiological response to impaired insulin signaling." (PMID 36979367, 2023). "Further investigation into how NF-κB–oestrogen pathways intersect and influence sex-dependent insulin secretion and diabetes may have importance for addressing clinical inequalities in diabetes treatment." (PMID 37311878, 2023).